UBR4 (ubiquitin protein ligase E3 component n-recognin 4)
Diseases named in the same sentence as UBR4 in open-access papers (continued):
Sharing a sentence is not in itself a finding about the gene and the disease.
cancer (11 papers, 2016 to 2026). A tumor composed of atypical neoplastic, often pleomorphic cells that invade other tissues. "The C-lobe of calmodulin, which is bound to calcium, captures an exposed UBR4 helix that fits the calmodulin-binding consensus and contains Arg residues mutated in cancer and ataxia." (PMID 40328314, 2025). "This interaction centres on UBR4 Met4444, Leu4447 and Arg residues mutated in cancer cells, which engage a surface centred on Leu8 of ubiquitin." (PMID 40328314, 2025). "Disease associations include neurological disorders and myofiber atrophy, and UBR4 loss increases cancer cell susceptibility to apoptosis." (PMID 38182926, 2024). "UBR4 is a 574 kDa E3 ligase (E3) of the N-degron pathway with roles in neurodevelopment, age-associated muscular atrophy and cancer." (PMID 38182926, 2024). "Through genetic and proteomic screening, we identify UBR4, UBR5, and HUWE1 as key ubiquitin E3 ligases marking cancer-associated A3B and A3H-I for degradation, thereby limiting A3-driven hypermutation." (PMID 41554709, 2026). "Correspondingly, UBR4, the ubiquitin protein ligase E3 component n-recognin 4, is involved in cancer cell growth." (PMID 30809043, 2019). "Whether UBR4 exhibits general oncogenic properties or cancer-type specificity, as seen in LUAD, remains to be determined." (PMID 40531870, 2025). "Targeting the UBR4–mitophagy pathway presents promising therapeutic opportunities for LUAD and other diseases associated with mitochondrial dysfunction, potentially paving the way for innovative cancer treatments." (PMID 40531870, 2025). "The discovery of a convergence point for multiple quality control pathways may explain why aneuploid cells are especially sensitive to loss of UBR4 or KCMF1 and identifies a potential vulnerability across many cancers." (PMID 39879985, 2025). "Finally, the enhanced crosslinking and immunoprecipitation (eCLIP) analyses reveal that FXR1 binds with the G4-enriched mRNA targets such as AHNAK, MAP1B, AHNAK2, HUWE1, DYNC1H1 and UBR4 and controls its mRNA expression in cancer cells." (PMID 38709899, 2024). "Although low-risk and non-cancer-associated E7 proteins engage both PTPN14 and UBR4, we hypothesize that the more robust interaction of high-risk E7 with both proteins is responsible for the high-risk E7-specific degradation of PTPN14." (PMID 27651363, 2016). "Our study provides novel insights into the physiological significance of UBR4-regulated MLH1 turnover and a new anti-cancer strategy avenue." (PMID 39032648, 2024).
tumor (6 papers, 2018 to 2025). "The present study also indicates that UBR4 loss causes cell cycle arrest as an initial response to oncogenic stimuli, potentially serving as a tumor suppression mechanism." (PMID 40531870, 2025). "It is possible that the tumor-promoting ability of the UBR4–mitophagy axis is suppressed under normal conditions by endogenous antagonists or inhibitory proteins but activated by cellular endoproteolytic mechanisms." (PMID 40531870, 2025). "Although these relationships are complex, our findings collectively suggest that UBR4 actively functions as a sensor of dynamic environmental changes, maintaining mitochondrial dynamics and metabolic pathways in tumor cells." (PMID 40531870, 2025). "UBR4 is overexpressed in the skeletal from fasted mice and genetic ablation of UBR4 preserves muscle mass in tumor-bearing mice." (PMID 33466753, 2021). "Intriguingly, the protection of UBR4 knockout against tumor-induced atrophy was limited to type IIA fibers." (PMID 33466753, 2021). "Consistently, tissue microarray (TMA) analysis of human tumor tissues revealed that UBR4 expression significantly correlated with LUAD progression and with levels of PTEN-induced putative kinase 1 (PINK1), a crucial mediator of mitophagy-mediated mitochondria quality control." (PMID 40531870, 2025). "In LUAD patients, UBR4 levels correlated with tumor stage, mitophagy markers, and poor survival." (PMID 40531870, 2025). "An unbiased analysis using The Cancer Genome Atlas (TCGA) datasets revealed that UBR4 mRNA expression was significantly higher in LUAD tumor samples (N = 510) than that in normal lung tissue samples (N = 59; P = 0.0014 from unpaired and P = 0.0085 from paired Student t tests)." (PMID 40531870, 2025). "Interestingly, UBR4 inactivation impairs tumor growth by disrupting mitochondrial dynamics but promotes inflammation linked to senescence." (PMID 40531870, 2025). "Additionally, UBR4 promotes ubiquitination of ATP-citrate lyase (ACLY), a key regulator of fatty acid biogenesis, suggesting that UBR4 has a role in tumor progression and lipid synthesis." (PMID 30157281, 2018). "We observed significantly elevated UBR4 and reduced CDKN1A expression in human LUAD tumor tissues from clinical databases." (PMID 40531870, 2025). "Knockdown of NAP1L1 promoted the ubiquitin-mediated degradation of BIRC2 through the ubiquitin–protein junction of UBR4, which in turn inhibited the proliferation and apoptotic escape of HCC cells and exerted anti-tumour effects." (PMID 38538582, 2024). "Similar to UBR4-mediated ubiquitylation, Cullin 3 containing E3 ligase complex has also been reported to ubiquitylate ACLY at Lys546 which inhibits lipid synthesis and tumor progression." (PMID 31534141, 2019).
infection (5 papers, 2013 to 2025). The state of being infected such as from the introduction of a foreign agent such as serum, vaccine, antigenic substance or organism. "This suggests that the change in abundance due to infection is most likely a change in ubiquitination state of UBR4, potentially allowing ISAV, a virus with demonstrated antagonistic non-structural proteins, to escape interferon response." (PMID 41181121, 2025). "At 12 hours post infection, as expected, the levels of UBR4 were decreased in the UBR4-knockdown cells compared to control cells." (PMID 23555265, 2013). "In addition, more DENV was present in control cells than in UBR4-knockdown cells at 48 hours post infection." (PMID 23555265, 2013).
UBR4 also shares sentences with these, for which no sentence is quoted: hepatocellular carcinoma (2 papers); Bladder Cancer (1); breast tumor (1); cryptorchidism (1); developmental delay (1); Intellectual disability (1); male infertility (1); myeloid neoplasm (1); Myokymia (1); neurological disorder (1); rheumatoid arthritis (1); stomach cancer (1); Vertigo (1).